MX1 (MX dynamin like GTPase 1)
Diseases named in the same sentence as MX1 in open-access papers (continued):
Sharing a sentence is not in itself a finding about the gene and the disease.
COVID-19 (92 papers, 2020 to 2026). A disease caused by infection with severe acute respiratory syndrome coronavirus 2. "Compared with the CG haplotype, the AT haplotype comprised of MX1 rs17000900-rs2071430 was associated with protection from severe COVID-19 (P = 6.3E-03, OR = 0.21, 95%CI = 0.07–0.64)." (PMID 38429664, 2024). "As previous studies reported, another five SNPs at the TMPRSS2/MX1 locus were correlated with a reduced risk of developing severe COVID-19 with the high level of MX1 expression in blood." (PMID 38429664, 2024). "In our study, we found that the MX1 rs17000900 CA + AA genotype tended to be correlated with a reduced risk of severe COVID-19 than the CC genotype in males." (PMID 38429664, 2024). "IFN signaling gene MX1 rs17000900 CA + AA genotype was correlated with a reduced risk of severe COVID-19 in males (P = 0.001, OR = 0.050, 95%CI = 0.008–0.316)." (PMID 38429664, 2024). "After the Bonferroni correction, the stratified analysis found that MX1 rs17000900 CA + AA genotype was related to a reduced risk of severe COVID-19 compared to the CC genotype in males (P = 0.001, OR = 0.050, 95%CI = 0.008–0.316), but it was not significant in females." (PMID 38429664, 2024). "Moreover, it has been proved that five single nucleotide polymorphisms (SNPs) within TMPRSS2 and near MX1 gene show associations with severe COVID-19." (PMID 37287057, 2023). "Older patients have a high risk for COVID-19-associated cytokine storms, suggesting that low MX1 expression could play a vital role in the cytokine storm." (PMID 35625619, 2022). "In line with this, elevated protein levels of ISG15 and MX1 have been found in the sera of COVID-19 patients, while increased protein levels of MX1 were found in the placental proteome profiles of women with lupus." (PMID 40574053, 2025). "To further interrogate type I IFN signaling in critical COVID-19 patients, we quantified protein expression of interferon-stimulated genes (ISGs) MX1, IRF7, and IFIT1 by flow cytometry." (PMID 38231281, 2024). "Our study found a possible association between MX1 and FOXP4 polymorphisms and the severity of COVID-19." (PMID 38429664, 2024). "The MX1 expression level was higher in COVID-19 patients, and its expression reduced significantly with age, which supported increasing severity in older patients." (PMID 38429664, 2024). "The AT haplotype comprised of MX1 rs17000900 and rs2071430 was more likely to protect against COVID-19 severity (P = 6.3E-03)." (PMID 38429664, 2024). "The AT haplotype consisting of MX1 rs17000900 and rs2071430 was likely to protect against COVID-19 adverse outcomes." (PMID 38429664, 2024). "This is the first time that MX1 gene (rs469390) is related to COVID-19 and proved its utility as expression biomarker between asymptomatic and severe patients." (PMID 37287057, 2023). "Our main aim is to try a molecular characterization in these main related genes (TMPRSS2, AR, ACE2 and MX1) to better understand COVID-19 severity; and trying to initiate the lines for molecular biomarkers in COVID-19 management." (PMID 37287057, 2023). "In COVID-19, MX1 is up-regulated with increasing viral load, and functionally, the SARS-CoV-2 protein ORF6 can suppress MX1 induction." (PMID 36757924, 2023). "The result of a COVID-19 case-control study revealed that MX1 expression was increased depending on elevated viral load, and the expression was decreased in elderly patients." (PMID 35625619, 2022). "ISG15, STAT1 and MX1 are the most conserved up-regulated genes across COVID-19 datasets of immunological cells." (PMID 36553678, 2022). "The study found that the expression of MX1 was significantly increased in COVID-19 patients compared with non-COVID-19 patients and increased with the viral load." (PMID 36212830, 2022).
COVID-19 (continued). "In large airway tissues, genes related to the mucosal layer (MUC4, MUC5AC, MUC5B) as well as cytokine-mediated signaling pathway genes (CCL20, CXCL1, CXCL6, CXCL6, MMP1) and type I interferon genes (IFIT3, ISG15, STAT1, MX1) were upregulated in COVID-19." (PMID 35233546, 2022). "Since MX1, MX2, ISG15, and OAS1 showed a similar expression pattern in COVID-19-positive patients, we next evaluated the association of their combined expressions with viral load." (PMID 36298734, 2022). "A study of red blood cells’ methylome demonstrated a hypomethylation of MX1 in samples from COVID-19-hospitalized patients, highlighting the relevance of the INF-γ pathway modulation during SARS-CoV-2 infection." (PMID 36298734, 2022). "In particular, MX1 is highlighted as a critical responder in SARS-CoV-2 infection with its expression levels being higher in COVID-19 than in non-COVID-19 patients and strikingly correlated to viral load increment." (PMID 34361874, 2021). "Albeit to a lesser extent, IL-1RAP, OASL and MX1 genes, which belong to the “senescence associated secretory phenotype” (SASP), were also found significantly upregulated in acute COVID-19 vs. HC monocytes." (PMID 34572439, 2021). "Further analysis revealed that the antiviral molecule, Mx1 was significantly upregulated in K18 mice and appears to be a key innate host defense mediator in this line relative to all other groups as previously observed in critical COVID-19 patients." (PMID 40242753, 2025). "However, Innate immune signatures such as MX1, USP18, and ISG15 in the NP were associated with Ct value at admission of COVID-19 patients." (PMID 39172244, 2024). "Interestingly, we described a truncated isoform of MX1 protein, MX1-201, upregulated at the onset of COVID-19 in placebo group participants compared with ChAdOx1 nCoV-19 vaccinees." (PMID 38649734, 2024). "Similarly, decreased expression of multiple IFN-I-inducible genes including MX1, OAS3 and OASL has been associated with persistent symptoms after COVID-19." (PMID 38532465, 2024). "MX1 is reported as a gene product of interferon, which will play important roles in inflammation in the lower respiratory tract, which will be relevant for developing severe COVID-19 cases." (PMID 37287057, 2023). "MX1 expression levels were reported to be significantly increased in COVID-19 patients." (PMID 35110370, 2022). "Although the expression of MX1 and MX2 in patients with COVID-19 were significantly higher than those in non-COVID-19 groups, MX1 shows a greater positive correlation with patients with COVID-19 and may be more specific than MX2 in response to SARS-CoV-2." (PMID 35620480, 2022). "MX1 was also reported to be up-regulated in COVID-19 patients." (PMID 34777295, 2021). "We found an SASP including IL1RAP, OASL and MX1 genes significantly upregulated in acute COVID-19." (PMID 34572439, 2021). "In conclusion, our study found that the MX1 gene promoter variant tended to be associated with a reduced risk of developing severe COVID-19 in males, and the polymorphisms near FOXP4 were significantly associated with increased COVID-19 severity in the Guangdong population." (PMID 38429664, 2024). "Furthermore, we also found that ACE2, MX1 and TMPRSS2 TAA could work as a protective role contrasting with CAA significantly associated with an increased risk of developing severe COVID-19." (PMID 37287057, 2023). "As MX1 is a key mediator of the interferon-induced antiviral response against a wide range of viruses this may contribute to the better outcome of CC/CT patients with COVID-19." (PMID 36927455, 2023). "Importantly, this suggests that MX1 may be a therapeutic target and that host genetic variables can affect the clinical manifestations of COVID-19." (PMID 35193695, 2022). "Interestingly, elevated MX1 levels were reported in COVID-19 patients." (PMID 35110370, 2022).
COVID-19 (continued). "In the acute hyperinflammatory phase, distinct subsets of monocyte-like cells (CD163+SLC39A8+CALR+ infMonos) and Tinf cells (MX1+IRF1+ISG15+) emerged, a phenomenon also observed in patients with sepsis and COVID-19." (PMID 40251340, 2025). "In severe COVID-19 cases (both SevereA and SevereD), NK cells exhibit significantly higher expression levels of IFNγ, while interferon-stimulated gene 15 (ISG15), and Myxovirus resistance protein 1 (MX1) were highly expressed in moderate cases." (PMID 39928675, 2025). "The identification of IFIT1, IFITM1, IRF7, ISG15, MX1, and OAS2 as pivotal components suggested their viability as potential drug targets for COVID-19." (PMID 40552037, 2025). "The top enriched clusters across SARS-CoV-2/COVID-19 studies included genes OAS1-3, IFIT3, SAMHD1, and MX1 involved in the innate immune response, interferon signaling, and defense response to the virus." (PMID 41227320, 2025). "The Protein-Protein Interaction analysis identified DDX58, MX1, and STAT1 as central genes in the context of COVID-19 and TB." (PMID 39639868, 2024). "In this study, the highest differentially expressed genes in COVID-19 (+) tissue, including ISG15 itself, IFIT1, RSAD2, OAS1, MX1, OASL, and IFIT3, are all important for the ISG15 pathway’s progression and are part of the lung tissue’s antiviral response." (PMID 38932146, 2024). "We found that upregulated expression of MX1, and RSAD2 was a prognostic factor of COVID-19 treatment." (PMID 39172244, 2024). "Research has found that, compared to a control group, serum levels of PARC/CCL18 and GNLY (granulysin), as well as IgG levels against MX1 and METTL3, are elevated in patients with AA related to the COVID-19 vaccine." (PMID 39021569, 2024). "The interferon (IFN)-stimulated 15 KDa protein (ISG15) had the largest increase in serum of COVID-19 patients, followed by several other IFN-induced proteins, such as ILF2, MX1, ISG20, LAP3, and UBE2L6." (PMID 37739942, 2023). "Here we characterize the role of ACE2, AR, MX1, ERG, ETV5 and TMPRSS2 for trying a better classification of COVID-19 through knowledge of the disease mechanisms." (PMID 37287057, 2023). "Here we focus on TMPRSS2, and related genes ACE2, MX1, AR, ETV5 and ERG, by its own or combined with clinical data, as an easy and relevant classifier of COVID-19 aggressiveness." (PMID 37287057, 2023). "In addition, the methylation of CpG in MX1 is associated with the severity of HIV patients using cocaine in HIV infection studies, suggesting that MX1 methylation levels may be a reliable predictor of COVID-19 severity." (PMID 36212830, 2022). "We found that the most profound changes were in MX-1 and CXCL10 expression, which are key in COVID-19." (PMID 36143354, 2022). "Compared to healthy skin, COVID-19 explants exhibited significant expression of ISGs (IFI35, IRF7 and MX1), and this response was strongly reduced by H-151." (PMID 35045565, 2022). "Genes involved in antiviral activity (i.e., ISG15, MX1, OAS1) and hyper-responsiveness of the immune system (i.e., TNFAIP8L2) were over-expressed in neutrophils from deceased COVID-19 patients." (PMID 34012444, 2021). "A significant decrease was observed for FI44L, MX1, RSAD2, ISIG15, and IFIT1 indicating a dysregulated type I/III interferon response in COVID-19 patients with pneumonia with a downregulation of ISGs." (PMID 34197543, 2021). "Many of the genes previously identified as increased within all cells from COVID-19 participants, e.g., anti-viral factors IFITM3, MX1, IFI44L, and IRF1, are upregulated among SARS-CoV-2 RNA+ cells compared to matched bystanders." (PMID 34352228, 2021). "The hypermethylated genes with the lowest p values for hospitalized COVID-19 patients at inclusion (T1) vs. at 6 weeks post-inclusion (T2) were PARP9, ABCA1, MX1, OAS1, ARID5B, and the hypomethylated genes included TMEM131, ROCK1, IFNGR1, CFAP61, VRK2, and C6orf138." (PMID 41227320, 2025).
COVID-19 (continued). "ISGs, such as IFIT and IFITM, ISG15, IFIH1, MX1, IRF7, OAS 1-3, and STAT1 are recognized for enhancing IFN signaling, thereby contributing to antiviral activity, emerge as potential candidates for drug targets in COVID-19 treatment." (PMID 40552037, 2025). "Furthermore, studies have found that autoantibodies such as ANA (antinuclear antibodies), IgG-anti-MX1, and IgG-anti-METTL3 are elevated in patients with autoimmune diseases related to the COVID-19 vaccine." (PMID 39021569, 2024). "Several studies have revealed that MX1 is overexpressed in COVID-19 group compared to control group, due to the activation of MX1 responding to new viruses for which the body has no immune defense." (PMID 35958619, 2022). "Interestingly, given the important role of type I interferon (IFN-I) in COVID-19, we also found decreased expression of multiple IFN-I-inducible genes including MX1, OAS3, and OASL." (PMID 35027067, 2022). "Severe COVID-19 was shown to be related with five SNPs in the TMPRSS2 and neighboring MX1 genes." (PMID 35193695, 2022). "A 2020 study detailed the expression of MX1 in 403 patients with COVID-19 and 50 patients without COVID-19." (PMID 35620480, 2022). "Furthermore, results evidenced that COVID-19-positive patients with higher expressions of JAK2 and STAT1 showed increased MX1, MX2, ISG15, and OAS1 mRNA levels." (PMID 36298734, 2022). "Comparison of severe and mild Symptomatic COVID-19 cases revealed an upregulation of CD177, the neutrophil marker, CXCL16, MAPKMAPK2 and IRF2BP2 with downregulation of ISGs; IFIT, IFIT3, OAS1, OAS2, LY6E and MX1 in severe cases." (PMID 34824360, 2021). "Hence, the in-silico validation of our hub genes in those expression datasets pointed out that ISG15 and MX1 are the most conserved up-regulated genes across COVID-19 datasets of immunological cells, while OAS1 and MX1 are those with lower gene expression levels in tissue-specific healthy samples." (PMID 36553678, 2022). "Classical monocytes in severe COVID-19 were found to be accompanied by the IFN-I response that was characterized by the up-regulation of various interferon-stimulating genes (ISGs), including ISG15, IFITM1/2/3, ISG20, IFI27, and MX1 when compared to mild COVID-19." (PMID 36159873, 2022). "Finally, suppression of the viral response genes (MX1 (p < 0.05), SAMHD1 (p < 0.001), IFITM3 (ns)) occurred more in severe ventilation-associated COVID-19 cases compared to non-ventilated cases." (PMID 33633121, 2021). "Elevated ISGylation levels of MX Dynamin Like GTPase 1 (MX-1), a selective substrate of IFN-α/β, have been observed in symptomatic COVID-19 patients but not in asymptomatic or uninfected individuals, suggesting a role in cytokine storms and inflammation." (PMID 40103488, 2025). "Expression of MX1, MX2, ISG15, and OAS1 (four well-known IFN-stimulated genes (ISGs)) displayed upregulation in COVID-19-positive vs. -negative patients." (PMID 36298734, 2022). "With non-severe (non-ICU) COVID-19, there was increased expression of the viral entry gene (CTSL (p < 0.05)) and increased antiviral response genes (MX1 (p < 0.0001), SAMHD1 (p < 0.0001), TRIM25 (p < 0.01), IFITM3 (ns))." (PMID 33633121, 2021). "ACE2, MX1, and BSG/CD147 expression constitute a molecular signature that reliably differentiates COVID-19 and non-COVID-19 patients." (PMID 34494942, 2021). "Targeted proteomics to measure abundance levels of MX1, ISG15, STAT1, RIG-I, and CXCL10 detected proteomic signatures of interferon-mediated antiviral signaling that differentiated COVID-19-positive from COVID-19-negative cases." (PMID 34400346, 2021). "The expression of MX1, MX2, ACE2, and BSG/CD147 can cluster individuals with and without COVID-19 through principal component analysis, which indicated that the expression levels of MX1 and MX2 between patients with and without COVID-19 are remarkably different." (PMID 35620480, 2022).
COVID-19 (continued). "Notably, in the present work, we demonstrated that the expressions of the ISGs MX1, MX2, ISG15, and OAS1 were upregulated in COVID-19-positive vs. -negative patients." (PMID 36298734, 2022). "For patients with COVID-19 who were not admitted to ICU, there was a statistically significant relationship between viral defense genes and CTSL expression, the four predictors (MX1, TRIM25 SAMHD1 and IFITM3) accounted for 65.56% of the variance (adjusted R2 = 0.656, p-value = 8.796–11)." (PMID 33633121, 2021).